BDH2 (3-hydroxybutyrate dehydrogenase 2)
Diseases named in the same sentence as BDH2 in open-access papers:
BDH2 is named in the same sentence as 49 diseases in open-access papers, as found by Europe PMC text mining. Sharing a sentence is not in itself a finding about the gene and the disease. The quoted sentences say what the papers report.
gastric cancer (6 papers, 2020 to 2025). A primary or metastatic malignant neoplasm involving the stomach. "3-Hydroxybutyrate dehydrogenase 2 (BDH2) is a member of the short-chain dehydrogenase/reductase family and has been identified as a significant tumor suppressor in gastric cancer (GC)." (PMID 40258841, 2025). "Studies have found that BDH2-related diseases included α-methylacetoacetic aciduria, myelodysplastic syndrome, and gastric cancer." (PMID 35001849, 2022). "BDH2 stimulates ROS-induced cell apoptosis and autophagy in gastric cancer through the promotion of Nrf2 ubiquitination." (PMID 35001849, 2022). "Similarly, BDH2 facilitates the ubiquitination of Nrf2 by enhancing the interaction between Keap1 and Nrf2 in gastric cancer, leading to increased ROS accumulation, activation of cellular autophagy, and inhibition of gastric cancer progression." (PMID 39664581, 2024). "However, the role of BDH2 in gastric cancer (GC) remains largely unclear." (PMID 32605589, 2020). "Overexpression of BDH2 promoted NRF2 ubiquitination and significantly induces ROS-mediated apoptosis and autophagy in gastric cancer." (PMID 38402166, 2024).
lupus (6 papers, 2021 to 2024). "Recent studies have shown that miR-21 overexpression in CD4+T cells promote iron accumulation by inhibiting 3-hydroxybutyrate dehydrogenase 2 (BDH2) in lupus-susceptible mice." (PMID 39726588, 2024). "Using human cells and murine models, the authors demonstrated that miR-21 was overexpressed in lupus T cells and inhibited 3-hydroxybutyrate dehydrogenase-2 (BDH2)." (PMID 35499081, 2022). "Our previous work demonstrated that miR-21 targets BDH2 to promote iron accumulation in lupus CD4+ T cells." (PMID 35499082, 2022).
acute myeloid leukemia (5 papers, 2013 to 2022). Acute myeloid leukemia (AML) is a group of neoplasms arising from precursor cells committed to the myeloid cell-line differentiation. "In contrast, the expression of BDH2 was reported to be aberrantly high in patients with acute myeloid leukaemia and oesophageal carcinoma, which imply a tumour-specific effect of BDH2 expression." (PMID 31819181, 2020). "On the other hand, in acute myeloid leukemia (AML) patients BDH2 functions as an anti-apoptotic factor, high expression of which serves as an unfavorable prognostic factor in this disease." (PMID 31921677, 2019). "Studies have found that as an anti-apoptosis factor in humans, BDH2 is a novel factor for the poor prognosis of de novo cytogenetically normal acute myeloid leukemia (AML)." (PMID 35001849, 2022).
esophageal cancer (5 papers, 2016 to 2019). A primary or metastatic malignant neoplasm involving the esophagus. "It has also been found that the knockdown of lncRNA TP73-AS1 attenuates the proliferation of esophageal cancer cells and enhances their chemosensitivity by inhibiting the expression of 3-hydroxybutyrate dehydrogenase type 2 (BDH2)." (PMID 30643007, 2019). "BDH2 or lncRNA TP73-AS1 knockdown enhanced the chemosensitivity of esophageal cancer cells to and cisplatin." (PMID 28388588, 2017). "Our results show that lncRNA TP73-AS1 and BDH2 levels are generally upregulated in esophageal cancer tissues and are strongly correlated with tumor location or TNM stage in clinical samples." (PMID 26799587, 2016). "In addition, BDH2 or lncRNA TP73-AS1 knockdown enhanced the chemosensitivity of esophageal cancer cells to 5-FU and cisplatin." (PMID 26799587, 2016). "BDH2 was found to be elevated and positively correlated with TNM stages in patients with esophageal cancers as well." (PMID 31921677, 2019). "lncRNA TP73-AS1 and its target gene BDH2 were both up-regulated and closely correlated with the tumor location and TNM stage in esophageal cancer tissues." (PMID 28388588, 2017). "LncRNA TP73-AS1 knockdown inhibited BDH2 expression in EC9706 and KYSE30 cells, whereas BDH2 knockdown repressed esophageal cancer cell proliferation and induced apoptosis via the caspase-3 dependent apoptotic pathway." (PMID 26799587, 2016). "lncRNA TP73-AS1 knockdown inhibited BDH2 expression in EC9706 and KYSE30 cells, which could further inhibit esophageal cancer cell proliferation and induce cell apoptosis via the caspase-3 dependent apoptotic pathway both in vitro and in vivo." (PMID 28388588, 2017).
iron deficiency (3 papers, 2013 to 2022). "Depletion of iron by inhibiting BDH2 expression makes intracellular iron abnormally accumulated, resulting in iron deficiency in mitochondria, suggesting that BDH2 exerts a crucial influence to iron homeostasis inside the cells." (PMID 35001849, 2022).
liver cancer (3 papers, 2019 to 2024). An epithelial or non-epithelial malignant neoplasm that arises from the liver. "Downregulation of BDH2 gene expression in liver cancer causes decreased secretion of acetoacetate, leading to inability to prevent recruitment of tumor-associated macrophage, a step in oncogenic transformation." (PMID 31921677, 2019). "In hepatoma cells, BDH2 can promote mitochondrial apoptosis by upregulating the pro-apoptotic protein Bax and downregulating the anti-apoptotic protein Bcl-2 and can also induce apoptosis of liver cancer cells through a caspase 3-independent pathway." (PMID 39691718, 2024).
pancreatic cancer (3 papers, 2019 to 2020). "Under microarray study, many genes related to cell proliferation, growth and survival, and cancer, including colon cancer, pancreatic cancer, and acute leukemia, showed up- or downregulation in BDH2-KD THP1 cells." (PMID 32344823, 2020). "BDH2 was also overexpressed in pancreatic cancer tissue when compared with the adjacent normal tissue." (PMID 30643007, 2019). "In conclusion, we identified TP73-AS1 as an oncogene that plays a vital role in the metastasis of pancreatic cancer and found that it positively regulates BDH2 expression via the regulation of miR-141 expression in pancreatic cancer cells." (PMID 30643007, 2019).
Alzheimer disease (2 papers, 2023 to 2024). A progressive, neurodegenerative disease characterized by loss of function and death of nerve cells in several areas of the brain leading to loss of cognitive function such as memory and language. "Recent studies report BDH2 to be directly implicated in Alzheimer’s disease progression." (PMID 37503064, 2023).
hepatocellular carcinoma (2 papers, 2022 to 2024). A malignant tumor that arises from hepatocytes. "The process of cell proliferation is positively regulated by BDH2, and, as a tumor suppressor, BDH2 is down-regulated in hepatocellular carcinoma and participates in regulating cell apoptosis and autophagy." (PMID 35001849, 2022).
leukemia (2 papers, 2013 to 2020). A malignant (clonal) hematologic disorder, involving hematopoietic stem cells and characterized by the presence of primitive or atypical myeloid or lymphoid cells in the bone marrow and the blood. "Patients with higher BDH2 expression show a greater risk of leukemia progression (15.25% vs. 3.77%, lower expression; P = 0.017) and shorter leukemia-free-survival (medium LFS, 9 years vs. 7 years; P = 0.024), as do patients with a ferritin level ≥350 ng/mL." (PMID 32344823, 2020). "To assess whether higher BDH2 expression was related to the increase in blast cells associated with leukemia progression, we analyzed BM samples from 13 patients from whom we had collected BM samples for at least two different stages of MDS." (PMID 32344823, 2020). "Patients with high BDH2 expression showed a higher risk of leukemia progression, poorer IPSS-R scores, and shorter LFS when compared with patients with low BDH2 expression." (PMID 32344823, 2020). "Interestingly, the patients with high BDH2 expression showed a higher risk of leukemia progression, a poor IPSS-R risk, and shorter LFS when compared with patients with low BDH2 expression." (PMID 32344823, 2020). "Furthermore, we used THP1, an acute myelomonocytic leukemia cell line, to present the possible mechanism of BDH2-related leukemia transformation in vitro." (PMID 32344823, 2020). "This suggests that BDH2 expression is a prognostic factor for leukemia transformation but it is not strongly associated with blast number." (PMID 32344823, 2020). "To test if BDH2 can induce chemoresistance, we generated BDH2-KD leukemia cell lines." (PMID 23941109, 2013). "The impact of BDH2 was evaluated by using RNA interference-mediated BDH2-KD in THP1 and HL60 leukemia cell lines." (PMID 23941109, 2013). "In the present study, we investigated whether BDH2 can serve as a prognostic marker for MDS and act as a predictor for the progression of leukemia." (PMID 32344823, 2020).
Obesity (2 papers, 2019 to 2023). Accumulation of substantial excess body fat. "Tissue biopsies of BC patients have shown that BDH2 has a positive relation with obesity in BC." (PMID 37895140, 2023).
schizophrenia (2 papers, 2023 to 2024). A major psychotic disorder characterized by abnormalities in the perception or expression of reality. "Among the six candidate genes, four (BDH2, CLDND1, GAS8, and TRIP4) displayed DTU events in all schizophrenia samples, while the other two genes (LARP4 and NVL) showed significant DTU events in specific subgroups." (PMID 38508189, 2024). "Amongst the six candidate genes, four (BDH2, CLDND1, GAS8, TRIP4) displayed DTU events in all schizophrenia samples, while the other two genes (LARP4, NVL) showed significant DTU events in specific subgroups." (PMID 37503064, 2023).
anemia (1 paper, 2021). A reduction in the number of red blood cells, the amount of hemoglobin, and/or the volume of packed red blood cells. "Bdh2 null mice developed microcytic anemia and tissue iron overload, especially in the spleen, and exogenous supplementation with 2,5-DHBA alleviates splenic iron overload in Bdh2 null mice." (PMID 33898455, 2021).
autoimmune disease (1 paper, 2021). A disorder resulting from loss of function or tissue destruction of an organ or multiple organs, arising from humoral or cellular immune responses of the individual to their own tissue constituents. "Interestingly, the lead SNP at the MANBA/UBE2D3 locus, rs223486, is an intergenic variant located in a region (±500 kb) that harbors several other genes (CISD2, NFKB1, SLC9B1/2, BDH2 and CENPE) with reported inflammatory and autoimmune disease associations." (PMID 33402679, 2021).
Crohn disease (1 paper, 2021). A gastrointestinal disorder characterized by chronic inflammation involving all layers of the intestinal wall, noncaseating granulomas affecting the intestinal wall and regional lymph nodes, and transmural fibrosis. "Some ICGs, such as BDH2, CYP4V2, OIT3, PLD1 and SLC25A23, were reported as differentially expressed in ileum tissue from Crohn’s disease vs. non-inflammatory bowel disease control." (PMID 34098982, 2021).
gonococcal infection (1 paper, 2014). "We found that gonococcal infection downregulated BDH2 gene expression in human THP-1 monocytes as assessed by qRT-PCR." (PMID 24489950, 2014). "Further, we found that gonococcal infection in primary monocytes led to significant downregulation of ferroportin and BDH2 gene expression." (PMID 24489950, 2014). "We now report that N. gonorrhoeae can survive intracellularly or in association with monocytes and macrophages, and that gonococcal infection of these cells upregulates expression of hepcidin, NGAL, and NRAMP1 and downregulates BDH2 and ferroportin expression." (PMID 24489950, 2014). "Our findings suggest that BDH2 may be a new key player in the iron-limiting innate immune defenses against gonococcal infection in macrophages." (PMID 24489950, 2014).
ischemic heart disease (1 paper, 2024). "The results of the mediated MR analyses indicate that potassium may reduce the risk of ischemic heart disease by influencing the expression of the plasma proteins BDH2 and C1R." (PMID 39691718, 2024).
lymph node metastasis (1 paper, 2020). "The results showed that low expression of BDH2 was positively associated with the TNM stage, depth of invasion, and lymph node metastasis, but not with other clinicopathological features including gender, age, differentiation, tumour localization, or tumour size." (PMID 32605589, 2020).
nasopharyngeal carcinoma (1 paper, 2020). A carcinoma arising from the nasopharyngeal epithelium. "Here we aim to explore the expression and possible function of BDH2 in nasopharyngeal carcinoma (NPC)." (PMID 31819181, 2020).
tumor (13 papers, 2012 to 2025). "We also found that the transcription of BDH2 was downregulated in a variety of tumours, indicating that the lower expression of BDH2 is universal in malignancies." (PMID 31819181, 2020). "Accordingly, IHC revealed that BDH2 overexpression downregulated the expression of p-AktSer473 and p-mTORSer2448 in xenografted tumours." (PMID 32605589, 2020). "Altogether, our data support a role of BDH2 as a tumour-suppressor gene in NPC." (PMID 31819181, 2020). "IHC of tumours confirmed the increased expression of BDH2 in tumours from BDH2–5–8F cell lines." (PMID 31819181, 2020). "Our study indicates that BDH2 is an important tumour suppressor in GC." (PMID 32605589, 2020). "BDH2-induced ROS accumulation suppresses phosphorylation of AktSer473 and mTORSer2448 by promoting ubiquitination of Nrf2, thereby inhibiting the growth of GC cells and playing a tumour-suppressive role." (PMID 32605589, 2020). "Expression of mRNA for Lcn2, Mmp9, Bdh2, 24p3R, megalin (another receptor mediating cellular uptake of lipocalin-2), and transferrin receptor (Tfrc) were determined in each tumor and reported as mean of all tumors/tissue samples in each of the four groups of mice." (PMID 22737251, 2012). "To date, what causes BDH2 inactivation in tumour has not been addressed yet." (PMID 31819181, 2020). "Our findings suggest that BDH2 may be a candidate tumour-suppressor gene in NPC." (PMID 31819181, 2020). "In addition, BDH2 protein expression levels are correlated with tumor size." (PMID 31921677, 2019). "Poor expression of BDH2 in HCC mediates unfavorable prognosis, poor tumor differentiation, high tumor volume, and venous invasion." (PMID 36759819, 2023). "3-hydroxybutyrate dehydrogenase 2 (BDH2) is downregulated in HCC and is responsible for reducing tumor cell progression." (PMID 36759819, 2023). "To reveal the potential role for BDH2 in NPC, we examined the mRNA expression of BDH2 in NPC primary tumours and NPC cell lines by real-time RT-PCR." (PMID 31819181, 2020). "In addition, the expression of 3-Hydroxybutyrate Dehydrogenase 2 (BDH2), a factor in triggering apoptosis and suppressing autophagy, is downregulated in tumor promotion stages." (PMID 38846985, 2024). "The main limitation of this study was the evaluation of other ketolytic enzymes including 3-hydroxybutyrate dehydrogenase 1(BDH1), 3-hydroxybutyrate dehydrogenase 2 (BDH2) and succinyl CoA: 3-oxoacid CoA transferase 1 (OXCT1) in the tumour and pre-tumour tissues of the OSCC patients." (PMID 36816175, 2023). "Early, we showed that the use of exogenous acetoacetate does not affect the migration of NPC cells, which suggests that the tumour-suppressor function of BDH2 still does not rely on acetoacetate production." (PMID 31819181, 2020).
cancer (5 papers, 2020 to 2025). A tumor composed of atypical neoplastic, often pleomorphic cells that invade other tissues. "BDH1 promotes the malignant cell phenotype by mediating the H3K9bhb/LRRC31 axis, while BDH2 functions as an anti-cancer agent by facilitating cell autophagy and apoptosis." (PMID 39857793, 2025). "3-Hydroxy butyrate dehydrogenase 2 (BDH2) is a short-chain dehydrogenase/reductase family member that plays a key role in the development and pathogenesis of human cancers." (PMID 32605589, 2020). "Another member of the BDH family, BDH2, is downregulated in various types of cancer." (PMID 39857793, 2025). "BDH2 was found to play a key role in the pathogenesis of various cancers." (PMID 35164665, 2022).
infection (4 papers, 2014 to 2022). The state of being infected such as from the introduction of a foreign agent such as serum, vaccine, antigenic substance or organism. "Specifically, its infection of macrophages reduced gene expression for ferroportin and BDH2 while increasing that for NRAMP1 and NGAL." (PMID 24489950, 2014). "Downregulation of BDH2 during infection is due to activation of hepcidin and intracellular iron retention, indicating an important role for BDH2 in iron-limiting innate immunity and host defense." (PMID 25762501, 2014). "Bdh2−/− mice showed no increased susceptibility to M.tb in a low dose infection model 150 days post-infection, however, 4 weeks post-infection Bdh2−/− mice had much lower lung CFU compared to WT mice." (PMID 30534124, 2018). "Results similar to those in monocyte experiments were obtained; GC-FA19 infection induced nitric oxide release and upregulated murine HAMP1 (the hepcidin homologue), LCN2 (the NGAL homolog) and NRAMP1 expression from infected macrophages, while it downregulated expression of the murine BDH2 gene." (PMID 24489950, 2014).
bacterial infection (3 papers, 2014 to 2019). "Moreover, NGAL expression is upregulated whereas BDH2 expression is downregulated in macrophages upon bacterial infection with Neisseria gonorrhoeae." (PMID 25762501, 2014).
cardiac diseases (2 papers, 2021 to 2024). "We found that potassium decreased the risk of ischaemic heart disease by reducing C1R and BDH2 expressions." (PMID 39691718, 2024).
BDH2 also shares sentences with these, for which no sentence is quoted: melanoma (2 papers); acute leukemia (1); breast carcinoma (1); cholangiocarcinoma (1); colon cancer (1); endocervical carcinoma (1); esophageal squamous cell carcinoma (1); essential hypertension (1); fungal infection (1); glioma (1); heart failure (1); hyperglycaemia (1); inflammatory bowel disease (1); kidney diseases (1); lung squamous cell carcinoma (1); migraine (1); myelodysplastic syndrome (1); neuromuscular disease (1); oesophageal cancer (1); osteoarthritis (1); ovarian carcinoma (1); prostate adenocarcinoma (1); prostate carcinoma (1); rheumatoid arthritis (1); steatosis (1).